Y_RNA (Y RNA )
Gene: Miscellaneous RNA gene on chromosome 11 (8,877,417 to 8,877,518, reverse strand). Ensembl gene ENSG00000202276.
Homologues: Orthologues: chimpanzee Y_RNA (100% identical), macaque Y_RNA (97% identical). Paralogues in human: Y_RNA (91% identical), RNY3 (90% identical), Y_RNA (90% identical), Y_RNA (89% identical), Y_RNA (88% identical), RNY3P1 (87% identical), Y_RNA (87% identical), Y_RNA (86% identical), Y_RNA (85% identical), Y_RNA (84% identical), RNY3P11 (83% identical), RNY3P16 (83% identical), and 97 more.